APOE (apolipoprotein E)
Diseases named in the same sentence as APOE in open-access papers (continued):
Sharing a sentence is not in itself a finding about the gene and the disease.
atrial fibrillation (21 papers, 2012 to 2025). A disorder characterized by an electrocardiographic finding of a supraventricular arrhythmia characterized by the replacement of consistent P waves by rapid oscillations or fibrillatory waves that vary in size, shape and timing and are accompanied by an irregular ventricular response. "The relationship between the APOE gene polymorphism and lipid profiles and atrial fibrillation (AF) remains controversial." (PMID 34587962, 2021). "The aim of the study was to examine the expression profile of genes (APOE, FTO, and LPL) associated with metabolic syndrome (MetS) in subjects with concomitant atrial fibrillation (AF)." (PMID 39166676, 2024). "This study is the first to report on the expression of the APOE gene in atrial fibrillation." (PMID 39166676, 2024). "Other risk factors such as APOE genotype, atrial fibrillation, or unmeasured aspects of care were not considered due to unavailability of the data." (PMID 34893555, 2022). "Compared with APOE non-ε4 carriers, APOE ε4 carriers were strongly associated with poor functional outcome (OR = 4.62, 95% CI 3.51–6.09, p < 0.001) overall after adjustment for age, gender, smoking, baseline NIHSS score, LDL level, atrial fibrillation, NLR and homocysteine." (PMID 36640294, 2023). "Correlation analysis of gene expression of APOE, FTO, and LPL genes with the clinical parameters of atrial fibrillation in studied groups." (PMID 39166676, 2024). "Significant APOE-ε4 interaction models were attenuated when excluding participants with prevalent CVD and atrial fibrillation but remained when excluding outliers." (PMID 33240156, 2020). "Third, although we controlled for many confounders, we cannot rule out the possibility of residual confounders such as atrial fibrillation, body mass index, air pollution, and apolipoprotein E genotype." (PMID 37280632, 2023). "Results for models stratified by APOE-ε4 status were similar when excluding participants for prevalent CVD and atrial fibrillation (data not shown), and when excluding outliers." (PMID 33240156, 2020).
cerebral infarction (21 papers, 2013 to 2025). An ischemic condition of the brain, producing a persistent focal neurological deficit in the area of distribution of the cerebral arteries. "Compared with patients with nCMBs, cerebral infarction patients with CMBs had higher APOE ε2 or ε4 allele carrier rates (p < 0.05)." (PMID 34660786, 2021). "Evidence from a meta-analysis included 29 studies suggested that APOE E4 allele was associated with an increased risk of developing cerebral infarction in Chinese population." (PMID 26830841, 2016). "A meta-analysis included 29 studies involving 2,737 CI cases and 2,689 controls suggested that APOE E4 allele was associated with an increased risk of developing cerebral infarction in Chinese population." (PMID 24456740, 2014). "While APOE-ε4 is correlated with lobar microbleeds, APOE-ε2 increases the risk of brain infarct." (PMID 37434208, 2023). "This study indicated that the APOE SNPs rs429358 and rs7412 may be associated with susceptibility to cerebral infarction in southern Chinese Hakka population." (PMID 32891149, 2020). "These variables were as follows: smoking, cardiac disease, drug-induced hallucination history, HAMA score, orthostatic hypotension, plasma APOE level, preoperative silent brain infarction or ischemia, MAOBIs, use of etomidate, and use of dexamethasone." (PMID 36483978, 2022). "However, the relationship between genetic polymorphisms of APOE and SLCO1B1 and cerebral infarction (CI) remains unclear." (PMID 32891149, 2020). "There were no significant age, sex, education, MMSE, GDS, CDR, apoE, global PiB index, or frequency of brain infarct among participants with (N = 27) or without (N = 30) WMH pathology." (PMID 23762308, 2013).
hemorrhage (21 papers, 2001 to 2025). Loss of blood from the vascular compartment to the exterior or into nonvascular body space as a result of rupture or severance of the blood vessels. "In contrast, a significant positive interaction was found for hemorrhages/microbleeds, indicating that the association between APOE ε4 and microbleeds strengthens with increasing age." (PMID 40382659, 2025). "Homozygosity for APOE ε2 is rare in the general population and has been associated with an elevated risk of hemorrhage in CAA, making this case particularly noteworthy." (PMID 40589441, 2025). "Other risk factors for subsequent ICH include age, microhemorrhage number, and APOE allele status (with both APOE ε2 and APOE ε4 being risk factors for hemorrhage in CAA, differing from ARIA in which only APOE ε4 is a risk factor)." (PMID 38592119, 2024). "The authors suggested that the APOE genotype ε2 may contribute to an increased risk of a hemorrhage after BAVM treatment (HR = 3.2; 95% CI = 1.0–9.7; P = 0.042)." (PMID 27026833, 2016). "Additionally, ApoE impacts the immunomodulatory and oxidative status, which may be associated with poor neurological outcomes after traumatic brain injury and hemorrhage." (PMID 30031394, 2018). "Conversely, we identified positive interactions between APOE ε4 and age at death for CAA and hemorrhages/microbleeds, suggesting that the influence of APOE ε4 on these vascular markers becomes more pronounced in older individuals." (PMID 40382659, 2025). "The observed pathological changes in the NC mice, ApoE−/−+agomir-NC-treated mice, and ApoE−/−+agomir-miR-19a/b-treated mice primarily manifested in the lung tissues, characterized by pulmonary hemorrhage and pulmonary edema." (PMID 38435118, 2024). "We summarized that SNPs of five inflammatory genes (IL6, APOE, IL1B, IL17A, MMP9) were reported to be associated with bAVM-related hemorrhage." (PMID 37065486, 2023). "In contrast, a significant positive interaction was observed for CAA (PRR: 1.00, 95% CI 0.99–1.00, p = 0.03) and hemorrhages/microbleeds (PRR: 1.03, 95% CI 1.01–1.05, p = 0.005), indicating that the association between APOE ε4 and microbleeds strengthens at older ages." (PMID 40382659, 2025). "This led to the identification of statistically significant association between bAVM-related hemorrhage and twelve heritable variants of seven genes (IL6, APOE, IL1B, IL17A, MMP9, EPHB4, and VEGFA) involved in the inflammatory and angiogenic signaling pathways." (PMID 37065486, 2023). "Remarkably, 5xFAD mice harboring the human APOE alleles (E3 and/or E4) exhibited cMBs related to CAA pathology, potentially due to the widely-known impact of the APOE gene as a risk factor for human CAA and CAA-related hemorrhage." (PMID 35563362, 2022).
psychosis (21 papers, 2012 to 2026). "Longitudinal data provided stronger evidence that psychosis follows the accumulation of multiple pathologies and genetic susceptibility (e.g., APOE ε4) and is associated with rapid cognitive decline." (PMID 40361900, 2025). "Existing evidence on the association between the APOE e4 allele and psychosis in AD is inconsistent." (PMID 38473892, 2024). "Significant associations were found between APOE ε4 genotype and both diagnosis and psychosis, since the proportion of ε4 carriers was higher in the AD-PS than in the AD-NP group (χ2 = 16.04, p < 0.001)." (PMID 35727357, 2023). "Although the interaction with APOE is consistent with MBI‐psychosis being linked to neurodegeneration, we cannot make any firm conclusions about etiology." (PMID 37139261, 2023). "When we considered the “Psychosis” endophenotype as whole, we confirmed the effect of APOE ε4 allele alone (risk mean = 20.7, 95% CI: 18.5–22.9), but also a “genexgene” interaction with MTHFR for both polymorphisms." (PMID 32823921, 2020). "In fact, genome-wide association studies (GWAS) have highlighted significant associations between psychosis in AD and multiple SNPs, including the APOE gene, supporting the hypothesis that a multifaceted genetic underpinning may underlie this phenotype." (PMID 35727357, 2023). "Indeed, another study demonstrated that carrying the APOE ε4 allele was correlated with earlier development of psychosis in PD patients, independently of cognitive status or age." (PMID 35741861, 2022). "Moreover, we found the involvement of APOE also in the “genexgene” interaction with MTHFR (both polymorphisms) as risk factors for “Psychosis”." (PMID 32823921, 2020). "In fact, we found an association of APOE also within “Hyperactivity”/”Psychosis” endophenotypes." (PMID 32823921, 2020). "Some studies have shown consistent associations between APOE ɛ4 and psychosis in AD." (PMID 33208795, 2020). "Furthermore, “Psychosis” and “Hyperactivity” resulted in the most severe endophenotypes, with APOE and MTHFR implicated as both single risk factors and “genexgene” interactions." (PMID 32823921, 2020). "One well-known risk factor for AD, particularly for late-onset AD (LOAD), that may increase the risk of developing psychosis in patients with AD is the E4 allele of the apolipoprotein E (APOE) gene." (PMID 23270420, 2012). "The hazard for MBI‐psychosis was higher in APOE ε4 carriers and there was an interaction between the two (HR for interaction: 3.4, 95% CI: 1.2–9.8, p = 0.02)." (PMID 37139261, 2023). "Here, we observed a similar interaction as for APOE (MBI‐psychosis*top tertile: HR: 7, 95% CI: 1.4–3.5, p = 0.02; MBI‐psychosis*middle tertile: HR: 3.4, 95% CI: 0.6–1.9, p = 0.6)." (PMID 37139261, 2023). "The interaction between the MBI‐psychosis group and APOE carrier status remained statistically significant (HR: 4.2, 95% CI: 1.4–12.1, p = 0.009)." (PMID 37139261, 2023). "The interaction between MBI‐psychosis and APOE ε4 was statistically significant (HR: 3.4, 95% CI: 1.2–9.8, p = 0.02)." (PMID 37139261, 2023). "The interaction between MBI‐psychosis group and APOE carrier status was statistically significant, with estimates similar to the primary analysis described earlier (HR: 3.8, 95% CI: 1.3–11.3, p = 0.02)." (PMID 37139261, 2023). "Studies suggest a strong genetic influence on psychosis in AD, suggesting an important role for apolipoprotein E4 (APOE4) and other genes like COMT and 5HT2A receptor polymorphism." (PMID 35939055, 2022). "An early study conducted in 1996 revealed that AD patients with an APOE 3/4 genotype had a more than three-fold increase in signs of psychosis compared to controls or AD patients with an APOE 3/3 genotype." (PMID 36139002, 2022). "The main results obtained in this work are represented by the involvement of APOE as a “single gene” in the modulation of the severity in agitation, also reflected in ”Psychosis” as well as in “Hyperactivity” endophenotypes, and in aberrant motor behavior." (PMID 32823921, 2020).
psychosis (continued). "Associations with APOE and MS4A for affective dysregulation, ZCWPW1, EPHA1, and BIN1 for psychosis-related symptoms, and NME8 for apathy highlight the possibility that MBI domains represent clinically observable phenotypes of underlying genetic susceptibilities." (PMID 41591092, 2026). "The Apolipoprotein E (APOE) genotype and the MS4A locus have been associated with affective dysregulation, ZCWPW1 with social inappropriateness and psychosis, BIN1 and EPHA1 with psychosis, and NME8 with apathy." (PMID 38473892, 2024). "Relin binds to the receptor for APOE, and might thus similarly modulate glutamatergic neurotransmission, altered in psychosis." (PMID 32823921, 2020). "Another more significant result of this work regarding the “genexgene” interactions between APOE and MTHFR (both polymorphisms) as risk factors for higher severity in the “Psychosis” endophenotype, underlies the important role played by MTHFR as a single gene in delusions (genotype CC of C677T)." (PMID 32823921, 2020). "In particular, APOE ε4 non-carriers along with the homozygotes CC (C677T) showed a high risk to develop psychosis (risk mean = 20.2, 95% CI: 18.9–29.3), but also with the homozygotes CC (C677T) and with the 1298A allele carriers (risk mean = 23.1, 95% CI: 18.7–27.6)." (PMID 32823921, 2020). "Active immunization of ApoE−/− mice against peptide fragments of GluN1 led to high circulating levels of NMDAR ABs and was able to induce psychosis-like symptoms upon MK-801 challenge." (PMID 33612107, 2021). "Previous studies examining the role of APOE4 in psychosis in AD have produced varied findings, with genetic association studies not finding a significant association between APOE and psychosis." (PMID 36139002, 2022). "We then created two strata for APOE status (by grouping carriers of one or two alleles together due to low numbers): no ε4 alleles (MBI‐psychosis, n = 160; No Psychosis, n = 1733) and one or two ε4 alleles (‘“ε4 carrier,” MBI‐psychosis, n = 91; No Psychosis, n = 766)." (PMID 37139261, 2023). "In APOE ε4 carriers, MBI‐psychosis had a lower survival probability relative to No Psychosis (9% [95% CI: 8%–29%] vs 6% [95% CI: 2%–10%, log rank p < 0.0001)." (PMID 37139261, 2023).
diabetic nephropathy (20 papers, 2012 to 2025). "Another study shows that treatment with the polyphenolic compounds proanthocyanidins reduced nephropathy in STZ-treated apolipoprotein E-deficient mice (“Proanthocyanidin attenuation of oxidative stress and NF-κB protects apolipoprotein E-deficient mice against diabetic nephropathy”)." (PMID 24222782, 2013). "Alternatively, the PPAR-alpha and -gamma agonists attenuate diabetic kidney disease in the apolipoprotein E knockout mice." (PMID 26821914, 2016). "The present study investigated the role of TRAIL in the pathogenesis of diabetic nephropathy using TRAIL-/-ApoE-/- mice." (PMID 24667560, 2014). "One study evaluating APOE isoforms, plasma lipid levels and remnant lipoproteins demonstrated their differential role in progression of diabetic nephropathy." (PMID 22874105, 2012). "Another study confirmed the associations of APOE allele E4 with the risk for T2D, CHD in T2D, and ICD in T2D, and also indicated that APOE allele E2 may be a risk factor for diabetic nephropathy." (PMID 38084238, 2023). "Therefore, we treated apolipoprotein E knockout mice (apoE KO) with streptozotocin to induce stable and reproducible diabetic nephropathy." (PMID 28103268, 2017). "Diabetic nephropathy, detected as increased albuminuria, creatinine clearance, mesangial expansion, oxidative stress, and fibrosis, was also significantly enhanced in diabetic ApoE/GPx1 dKO mice compared with diabetic ApoE KO controls." (PMID 22013533, 2012). "In a mouse model of streptozotocin‐induced diabetic nephropathy in ApoE−/− mice, the genetic deletion of NOX4 (but not NOX1), protected mice from structural and functional damage linked to diabetic nephropathy." (PMID 36658776, 2023). "However, several specific genetically modified mice with a C57/Bl6 background were shown to progress to diabetic nephropathy when diabetically-induced, such as the eNOS knockout in STZ-induced diabetic or db/db mice and the ApoE knockout in STZ-induced mice." (PMID 32753679, 2020). "Only one study provided the apoE gene frequencies in different etiologies of ESRD, and the subgroup analysis by etiology was not able to perform, especially about the influences of diabetic nephropathy and non-diabetic nephropathies." (PMID 24349494, 2013).
liver fibrosis (20 papers, 2012 to 2026). "Our study showed liver inflammation through macrophage activity, represented by the marker F4/80, hepatic lipid deposition, and hepatic fibrosis in OVX ApoE KO mice with a Western diet." (PMID 37372993, 2023). "The essential findings of the present study are that an anti-NLRP3 approach in NASH can arrest established liver fibrosis and chronic inflammation in ApoE-/- mice." (PMID 34513923, 2021). "Previously, we showed that progression of liver fibrosis correlated with plasma pro‐inflammatory cytokine levels and gene expression in the liver livers of ApoE*3‐Leiden.CETP mice." (PMID 34505423, 2021). "Given that the two pathways most increased at the mRNA levels in FCMs compared to NFMs were the LXR and hepatic fibrosis pathways, we used immunohistochemistry to validate these findings in sections of subcutaneous sponges from ApoE null mice." (PMID 26197235, 2015). "In addition to body weight gain, an increase was reported in fasting blood glucose, hepatic triglyceride, inflammation, and liver fibrosis in ApoE KO animals fed WD for 7 weeks." (PMID 36286035, 2022). "Given that MCD feeding induced hepatic fibrosis in ApoE-/- mice, we tested whether the inhibition of NLRP3 with IFM-514 had an effect on markers of fibrosis." (PMID 34513923, 2021). "It has been shown that 7 weeks of a Western diet in ApoE KO male mice promoted the development of NASH with liver fibrosis, and similar effects were observed in our study in OVX ApoE KO female mice." (PMID 37372993, 2023). "ApoE−/− mice fed with WD were comparable to the established MCD model with respect to liver inflammation and liver fibrosis." (PMID 26263022, 2015). "We evaluated these effects by feeding APOE*3-Leiden mice a Western-type diet (WTD) with or without atorvastatin to induce NASH and hepatic fibrosis." (PMID 37175538, 2023).